SIRT4 (sirtuin 4)
Diseases named in the same sentence as SIRT4 in open-access papers (continued):
Sharing a sentence is not in itself a finding about the gene and the disease.
tumor (continued). "Our results based on the clinical-pathological characteristics of patients with ccRCC showed that the expression of SIRT2, SIRT3, SIRT6, and SIRT7 was increased in tumor-stage 1-4 subgroups, SIRT1 was increased in tumor-stage 1, and the expression of SIRT4 and SIRT5was decreased." (PMID 37096064, 2023). "However, the two studies performed on human GC tissue agreed that its expression in GC tissue is significantly lower than in the adjacent normal tissue and that SIRT4 correlates with LNM and tumor stage." (PMID 36358890, 2022). "Our study describes, for the first time, the regulatory effect of SIRT4 on GDH enzyme activity in HSCs and demonstrates that SIRT4 inhibits glutamine metabolism in HSCs in a mechanism similar to that of tumor metabolic reprogramming and plays an antifibrotic role." (PMID 36376267, 2022). "To conclude, these published data suggest that similar to SIRT4, SIRT5 might have a tumor suppressor function in GC." (PMID 36358890, 2022). "This study shows that, similar to SIRT4 and SIRT5, SIRT6 expression is lower in GC tissue when compared to normal gastric tissue, and that its decreased expression correlates with tumor grade, tumor size, and TNM stage, along with decreased overall survival and DFS of GC patients." (PMID 36358890, 2022). "Sirt4 is also able to prevent the epithelial–mesenchymal transition (EMT) in CRC cells by upregulating the expression of E-cadherin, which promotes cell–cell adhesion and consequently inhibits tumor invasion and metastasis." (PMID 32373514, 2020). "Overall and distant relapse were significantly increased in SIRT4-negative tumours comparatively to SIRT4-positive tumours." (PMID 32429269, 2020). "In conclusion, down-regulation of expression of certain mitochondrial tumor-suppressor genes, such as SIRT3, SIRT4, and MTUS1, in HNSCC cells indicates aggressive tumor behaviors, and may predict an unfavorable clinical outcome." (PMID 33585187, 2020). "SIRT4 inhibits mitochondrial metabolism and SIRT1 expression to reduce tumor energy metabolism." (PMID 33585187, 2020). "In fact, while in non-cancer cells Sirt4 protects against the accumulation of DNA damage and promotes DNA repair by acting as a mitochondrial tumor suppressor, it seems to play a different role in cancer cells depending on the external conditions." (PMID 32373514, 2020). "When SIRT4 is absent, the cell will maintain division even when DNA damage occurs, making the cell accumulate more DNA damage, and eventually lead to tumor occurrence." (PMID 32194820, 2020). "SIRT4 expression was negatively correlated with tumor–node–metastasis (TNM) stage, but not with sex, age, venous invasion or histology type." (PMID 33585187, 2020). "Since SIRT1 has been reported to be involved in tumor initiation and progression as well as cancer stemness, we hypothesized that SIRT1 might be a potential target of SIRT4." (PMID 32863939, 2020). "Compared with the positive staining of the corresponding normal adjacent tissues, SIRT4-negative or weak staining was observed in most tumor types." (PMID 33585187, 2020). "Moreover, SIRT4 expression was down-regulated in the early stage and, importantly, its low expression was maintained during cancer progression, suggesting that down-regulation of SIRT4 expression may be necessary for tumorigenesis and maintenance of tumor cells." (PMID 33585187, 2020). "Therefore, SIRT4 is a promising target in HCC immunotherapy and reverses macrophage-induced immunosuppression in the tumour microenvironment." (PMID 31744516, 2019). "SIRT4, that besides other targets, inhibits PDH (pyruvate dehygrogenase) 9 and GDH (glutamate dehydrogenase) 10 as key anaplerotic enzymes feeding into the citric acid cycle, represents a metabolic tumor suppressor that is down-regulated in many cancer types." (PMID 31225445, 2017).
tumor (continued). "In conclusion, our study demonstrated that down-regulation of selected mitochondrial TS genes such as SIRT3, SIRT4 and MTUS1 in HNSCC indicate aggressive tumor behaviors and may predict an unfavorable clinical outcome." (PMID 26785117, 2016). "The immunohistochemistry staining showed that there was significant excessive expression of CtBP in tumor samples compared with surrounding non-tumor tissues, whereas SIRT4 expression in tumor tissues was abolished compared with the non-tumor tissues." (PMID 25633289, 2015). "In addition to these members of the ARTD family, recent studies revealed that SIRT4 possesses tumor suppressor function, whereas SIRT6 has been reported to have both tumor suppressive and promoting functions." (PMID 26426055, 2015). "This may be part of the mechanism behind SIRT3, SIRT4, and SIRT5 appearing to have tumor-suppressive effects." (PMID 25165814, 2014). "SIRT4 overexpression can prevent MYC-induced glutamine dependency and tumor growth." (PMID 25085992, 2014). "Whereas the preponderance of the evidence suggests that SIRT1 in many contexts promotes cancer metabolism by working in conjunction with HIF and MYC family proteins, SIRT3, SIRT4 and SIRT6 all inhibit distinct aspects of the metabolic alterations observed in tumor cells." (PMID 25085992, 2014). "Based on the findings that SIRT1 and SIRT4 transcripts show dynamic responses to induction of differentiation, SSL, and oxidative stress, we examined the expression of SIRTs in human normal, premalignant (AK), and tumor (SCC) skin biopsies." (PMID 22860104, 2012). "Mitochondrial SIRTs (SIRT3, SIRT4 and SIRT5) have been widely reported to regulate a variety of key biological processes, including gene expression, DNA damage repair, metabolism and survival, and have the Janus role in tumorigenesis, either tumor suppressive or oncogenic functions 122-124." (PMID 38773972, 2024). "Therefore, SIRT4 and SIRT5 potentially inhibit the occurrence and development of ccRCC, whereas high expression of SIRT3, SIRT6, and SIRT7 might have an important tumor-promoting role." (PMID 37096064, 2023). "Combined with SIRT expression (mRNA and protein) and the prognostic value of SIRTs (mentioned previously herein), we speculate that SIRT4 and SIRT5 might be possible tumor suppressor markers, whereas SIRT6 and SIRT7 could play an important role in promoting tumor development." (PMID 37096064, 2023). "SIRT-4 can regulate the phosphorylation of P38 mitogen-activated protein kinase (MAPK) to control reactive oxygen species (ROS) level and heme oxygenase-1 expression, change the tumor hypoxia microenvironment, promote the apoptosis of cancer cells, and play an anti-tumor effect." (PMID 35906622, 2022). "In short, similar to SIRT4 and SIRT5, SIRT6 might have a tumor suppressor function in GC." (PMID 36358890, 2022). "However, the role of SIRT4 as a tumor suppressor in the setting of HBV-induced HCC has not been explored." (PMID 33931611, 2021). "It is unknown, whether the tumor phenotypes of mice lacking SIRT3 or SIRT4 are primarily based on mitochondria-dependent and/or -independent (i.e., mitotic/microtubule-associated) mechanisms." (PMID 32846968, 2020). "Conclusions: miR-424-5p had tumor promoting functions in proliferation and migration of ESCC by targeting SIRT4, suggesting that miR-424-5p may serve as a potential diagnostic biomarker and manipulation of miR-424-5p/SIRT4 axis could provide a novel therapeutic strategy for further ESCC treatment." (PMID 33033517, 2020). "However, SIRT4 has not been proved to act as a tumor suppressor gene." (PMID 31817470, 2019).
cancer (74 papers, 2014 to 2025). A tumor composed of atypical neoplastic, often pleomorphic cells that invade other tissues. "SIRT4 downregulation has been observed in multiple cancer types, and this deficit in CRC is associated with poor prognoses, lower survival rates, and reduced chemosensitivity." (PMID 40290068, 2025). "Sirtuin 4 (SIRT4), a member of the sirtuin proteins family, has been implicated in the regulation of cancer cell toxicity through the modulation of glutamate dehydrogenase and enhancing the sensitivity of ER + BC cells to tamoxifen." (PMID 35154350, 2022). "SIRT4 has been implicated in regulating cancer cell toxicity by the modulation of glutamate dehydrogenase." (PMID 35154350, 2022). "Several lysine acetylation regulator genes showed oncogenic features, such as HDAC11 and SIRT4, and higher expression of these genes was associated with worse survival across cancer types." (PMID 34136387, 2021). "SIRT4 expression is down-regulated in most cancer types, and loss of SIRT4 increases the risk of spontaneous tumors throughout life." (PMID 33585187, 2020). "A recent study has also showed that SIRT4 is a crucial regulator of the stress resistance in cancer cells and SIRT4 loss sensitizes cells to DNA damage or ER stress." (PMID 27916001, 2016). "The downregulation of SIRT3 and SIRT4 may lead to enhanced acetylation status and ROS generation in mitochondria, which are tightly associated with higher cancer risk." (PMID 26785117, 2016). "Loss of SIRT4 appears to be a result of mammalian target of rapamycin complex 1 (mTORC1), a complex consisting of mTOR, Raptor, and mLST8 that is dysregulated in human cancers and activated under nutrient-rich conditions." (PMID 25332769, 2014). "In line with this, SIRT4 is downregulated in various cancer types, including breast, thyroid, lung, and prostate cancer." (PMID 39215785, 2025). "SIRT4, a uniquely functioning Sirtuin member, is involved in complex regulatory mechanisms in cancer biology." (PMID 40754534, 2025). "All of these events were accompanied by upregulation of the SIRT4 levels and p-AMPK activation, in accordance with other works which demonstrated the oncosuppressor role of SIRT4 in many cancers, including CRC." (PMID 40290068, 2025). "SIRT4 mRNA levels were reportedly reduced across several types of malignant tumor tissues, including those related to lung and bladder cancers." (PMID 39683482, 2024). "In NSCLC, SIRT4 inhibits cancer cell proliferation, invasion, and migration via disruption of mitochondrial fission and suppression of the function of the mitochondrial fission-associated protein Drp1." (PMID 39479446, 2024). "By inhibiting glutamine metabolism, SIRT4 restricts the availability of substrates that cancer cells rely on for rapid proliferation, thus acting as a metabolic checkpoint." (PMID 39682281, 2024). "The regulation of mitochondria, cell cycle, and regulated cell death constitutes integral components of SIRT4 anti-cancer mechanism." (PMID 39479446, 2024). "SIRT4 mRNA levels are reduced in human cancers such as pancreatic, gastric, ovarian, renal, prostate, liver, or lung cancers." (PMID 39479446, 2024). "The regulation of SIRT4 expression in cancer is complex, involving factors such as mTORC1-mediated degradation of CREB2, which controls SIRT4 transcription." (PMID 38773972, 2024). "SIRT4 (SIRT4) plays a significant role in cancer biology, primarily through its regulatory functions in metabolic processes and cellular stress responses." (PMID 39682281, 2024). "SIRT4 inhibits crucial glutamine metabolism for cancer cell growth, affecting metabolite availability and lipid metabolism." (PMID 38331199, 2024). "SIRT4 plays a key role in suppressing tumorigenesis in a variety of cancer types (e.g. colorectal, breast, prostate), consistent with its low expression levels in these tumors." (PMID 39479446, 2024).
cancer (continued). "Analysis of expression databases reveals SIRT4 downregulation in several human cancers, including breast, bladder, gastric, colon, thyroid, and ovarian cancers." (PMID 38773972, 2024). "The battle between SIRT4 and mammalian target of rapamycin protein complex 1 (mTORC1) is also interesting in the development of cancer." (PMID 39479446, 2024). "C-terminal binding protein (CtBP) promotes glutamine catabolism by directly suppressing the production of SIRT4, a glutamine catabolism repressor that enzymatically modifies glutamate dehydrogenase in mitochondria, in cancer cells." (PMID 39479446, 2024). "Several studies have shown that low levels of SIRT4 lead to an increase in glutamine metabolism and promotes the progression of cancer." (PMID 37175631, 2023). "In thyroid and gastric cancer cells, overexpression of SIRT4 blocks the progression of the cancer cell cycle by inactivating ERK, p-ERK, cyclin D (ACT/GSK3ß/CyclinD1 pathway) and cyclin E." (PMID 37175631, 2023). "It is, therefore, greatly interesting to further clarify which reasons lay a foundation for SIRT4 to differentially regulate cancer and other types of disease or physiology." (PMID 36209169, 2023). "It is well known that SIRT4 is a tumor suppressor gene, and its expression is down-regulated in cancer." (PMID 36209169, 2023). "PF mediates anti-cancer effects by activating sirtuin 4, and it also overcomes tamoxifen resistance in estrogen receptor-positive breast cancer." (PMID 38140352, 2023). "SIRT4 can inhibit tumorigenesis by inhibiting glutamine metabolism in mitochondria and is considered a potential target for cancer treatment." (PMID 35154350, 2022). "Despite this, there is increasing evidence suggesting that SIRT4 acts as a mitochondrial-localized tumor suppressor in various cancers such as breast cancer, prostate cancer, esophageal squamous cell carcinoma, and colorectal cancer." (PMID 33931611, 2021). "By contrast, in human PDA tumors, containing cancer and stromal cell types, nearly all HDACs (except SIRT4) and BETs (except BRDT, BRWD3, and CECR2) were highly expressed." (PMID 33244070, 2020). "The suppression of SIRT4 by mTORC1 has profound effects on the metabolism of cancer cells, specifically inhibiting glutamine metabolism through inhibition of GDH." (PMID 32292719, 2020). "To further address the role of SIRT4 in cancer stemness, we next generated MDA-MB-231, BT549, and SK-BR-3 cells overexpressing SIRT4, and MDA-MB-468, MCF-7 as well as MCF-10A cells knocking down endogenous SIRT4 via lentiviral shRNA." (PMID 32863939, 2020). "Sirt4 mRNA levels were reduced in several human cancers, such as small cell lung carcinoma, gastric cancer, breast cancer and leukemia." (PMID 32765955, 2020). "Analyses of data from The Cancer Genome Atlas (TCGA) database demonstrated that SIRT4 expression was downregulated in 30 cancer types." (PMID 33585187, 2020). "In this way, SIRT4 plays an irreplaceable part in the metabolic regulation of glutamine, lipids, and glucose in malignant tumors." (PMID 33585187, 2020). "Sirt4 can also display pro-apoptotic effects in lung cancer cells by inhibiting mitochondrial fission, which is known to prevent apoptosis and enhance cancer cell growth." (PMID 32373514, 2020). "Wang and colleagues studied the copy number of SIRT4 in various cancer types using the Tumorscape database, and found that SIRT4 was located in the region in chromosome 12 that was deleted significantly in the whole dataset." (PMID 33585187, 2020). "SIRT4 has important roles in energy metabolism and oxidative stress, metabolic diseases and cancer, physical fitness, health, and ageing." (PMID 33585187, 2020). "In this review, we summarize the structure and localization, enzyme activity, and role of SIRT4 in malignant tumors." (PMID 33585187, 2020). "Cancer is characterized as reprogramming of energy metabolism and redox imbalance, and SIRT4 can affect tumorigenesis." (PMID 33585187, 2020).
cancer (continued). "In pathologic grade-III carcinoma and all clinical stages, overexpression of SIRT4 mRNA was correlated with poor overall survival." (PMID 33585187, 2020). "SIRT4 has been largely reported to have protective roles against cancer by repressing glutamine metabolism and maintaining genomic stability." (PMID 31572453, 2019). "Further, it has been reported that SIRT4 expression was reduced in patients with cancers such as colon and gastric cancers." (PMID 31447696, 2019). "Together, these results suggest that SIRT4 is a potential regulator of the activation of certain compounds in cancer therapy and to play an important role in managing the players involved in the antioxidant responses." (PMID 31447696, 2019). "Analysis of RNA-seq data from 34 normal gastric tissues and 415 primary GC revealed significant upregulation of B7-H1; HDAC1–3, 6–8, and 10; and SIRT1, 3, 5, and 6 and downregulation of HDAC5 and SIRT4 in cancer (only data of B7-H1 and HDAC1–3 was presented)." (PMID 30537988, 2018). "Not surprisingly, there are many metabolic pathway regulators identified to be targets of CtBP transcriptional regulatory function including SIRT4 in the genome-wide profiling of CtBP targets in cancer cells." (PMID 29540733, 2018). "Here we further report that CtBP repression of SIRT4 expression is regulated by glycolysis activity in cancer cells and highlight a novel pathway that mediates the crosstalk between glycolysis and glutaminolysis." (PMID 29540733, 2018). "In the context of senescence triggered by Lsd1 inhibition, it is compelling to note that LSD1 and SIRT4 control proliferation in cancer cells." (PMID 28230862, 2017). "SIRT4 mRNA level was reduced in several human cancers, such as small cell lung carcinoma, gastric cancer, breast cancer and leukemia." (PMID 27916001, 2016). "In view of the critical role of CtBP in regulating glutaminolysis pathway and its positive influence on cancer cell growth via regulating SIRT4, we wonder if CtBP-regulated glutaminolysis pathway has global effect on cell metabolism." (PMID 25633289, 2015). "mTORC1 (mammalian target of rapamycin complex 1), which regulates protein synthesis and whose kinase activity is upregulated in many human cancers, alleviates SIRT4-induced inhibition of glutamine metabolism by suppressing SIRT4 expression." (PMID 25085992, 2014). "Recent evidence suggests that SIRT4 may act as a metabolic checkpoint by repressing glutamine metabolism and interacting with mTORC1, thereby influencing cancer cell growth and stress adaptation." (PMID 40290068, 2025). "Overall, SIRT4 exerts dual functions in cancer by modulating glutamine metabolism, suggesting its potential as a therapeutic target for cancer treatment, although further studies are needed to elucidate its precise mechanisms and therapeutic implications in different cancer contexts." (PMID 38773972, 2024). "Moreover, SIRT4’s expression levels have been correlated with clinical outcomes in various cancers, where lower levels often indicate more aggressive disease and poorer prognosis." (PMID 39682281, 2024). "This multifaceted regulation of cancer metabolism and mitochondrial integrity establishes SIRT4 as not only a metabolic gatekeeper but also a potent therapeutic target, warranting further exploration to refine treatment strategies for this aggressive malignancy." (PMID 39682281, 2024). "In addition, the regulatory role of SIRT4 in the glycolysis of different types of cancers has been widely demonstrated." (PMID 36712589, 2023). "In conclusion, these results highlight the potential application of SIRT4 in cancer therapy." (PMID 40625712, 2023). "To date, SIRT4 has mostly been studied in metabolic diseases and cancer." (PMID 36376267, 2022). "Nevertheless, SIRT4-knockout mice spontaneously developed cancers of liver, lung, and breast." (PMID 35842463, 2022).